NLRP3 (NLR family pyrin domain containing 3)
Diseases named in the same sentence as NLRP3 in open-access papers (continued):
Sharing a sentence is not in itself a finding about the gene and the disease.
melanoma (continued). "In mice with melanoma and lung cancer who underwent FMD cycles, the levels of inflammatory markers, including NLRP3 inflammasome and leukotriene, were observed to be decreased in both peripheral blood and the heart." (PMID 38473997, 2024). "In a mouse model of melanoma, NLRP3-/- mice that were vaccinated with DC-based vaccines had significantly increased survival compared to wild-type controls, possibly due to the presence of fewer MDSCs in NLRP3-/- mice, which may have contributed to impaired tumorigenesis." (PMID 37497237, 2023). "NLRP3 inhibition and anti-PD-1 treatment significantly increased the antitumor efficacy of monotherapy by limiting MDSC-mediated T cell suppression and melanoma tumor progression." (PMID 36911674, 2023). "In the survival analysis of the 19 cuproptosis-related genes in melanoma patients, seventeen cuproptosis-related genes have significant differences, while LIPT1 and NLRP3 showed the most significant differences." (PMID 37138850, 2023). "Recent studies have shown that the expression of NLRP3, AIM2 and caspase-1 was significantly increased in tumor specimens from melanoma patients who had been effectively treated with PD-1." (PMID 37497237, 2023). "Thymoquinone significantly decreased the expression of NLRP3 inflammasomes in B16F10 and A375 melanoma cells." (PMID 35682990, 2022). "This promotes anti-PD1 resistance through NLRP3 recruitment of immunosuppressive cell subsets, as observed in the BRAFV600E/PTEN melanoma model with subsequent induction of pyroptosis." (PMID 36376979, 2022). "These authors showed that a selective pharmacologic inhibitor of NLRP3, OLT1177, suppressed B16/F10 melanoma progression and inhibited IL-1β release in the 1205Lu human melanoma cell line." (PMID 34638239, 2021). "It appears also of great interest that in WM266-4 melanoma cells the SFN/FB combination inhibited inflammasome formation (i.e., NLRP3, cleaved caspase-1 and ASC expression) and IL-1β production significantly more than each single compound." (PMID 32486135, 2020). "For this reason, we evaluated the effect exerted by SFN and FB, administered individually or in combination, on the NLRP3 inflammasome components, as well as on the products of their activation (cleaved caspase-1 and IL-1β) in WM266-4 melanoma cells." (PMID 32486135, 2020). "Interestingly, TMEM176B was associated with diminished NLRP3 and IL1B expression in macrophages infiltrating human melanoma, suggesting that this ion channel may function as an innate checkpoint signal that hinders immune responses in the tumor microenvironment." (PMID 31085177, 2019). "Conversely, lung cancer, melanoma, breast cancer and HNSCC, demonstrated that NLRP3 inflammasomes, IL-1β and IL-18 promote tumor growth, proliferation, invasion and metastasis." (PMID 30447690, 2018). "Upon infection, activation of caspase 1 occurred via the NLR family pyrin domain containing 3 (NLRP3, recognising membrane damage) and absent in melanoma 2 (AIM2, recognising cytoplasmic DNA) inflammasome activation, which led to monocyte pyroptosis." (PMID 39273582, 2024). "This resulted in reduced melanoma tumour progression (p < 0.01) and while not yet been observed in OC, it is possible that the NLRP3 inflammasome drives a complex pro-inflammatory and pro-tumour environment." (PMID 39516433, 2024). "Once the external stimulus is recognized by pattern recognition receptors on the cell membrane and cytoplasm, it stimulates the activation of NLRP3, absent in melanoma 2 and other pyroptosis-related proteins." (PMID 37083810, 2023). "In addition, TGFβ, NLRP3 inflammasome, Oncostatin M and VEGF/VEGFR signaling pathway was enriched in melanoma DC, which has been shown to be inhibitory to DC maturation and function." (PMID 37938561, 2023). "Then, a cytosolic signal nucleates the inflammasome through activation of one of many sensors, including NLRP3, and absent in melanoma 2 (AIM)." (PMID 37113134, 2023).
melanoma (continued). "Studies showed that the expression of inflammasome NLR Family Pyrin Domain Containing 3 (NLRP3) and absent in melanoma-2 (AIM2) was increased in AD and was related to epidermal inflammation." (PMID 37330465, 2023). "In children with ASD, an increase in the NLRP3 inflammasome and another inflammasome complex, absent in melanoma 2, and accordingly the production of IL-1β and IL-18 inflammatory cytokines were observed." (PMID 38026692, 2023). "The tumor-suppressive effect of NLRP3 deficiency was not restricted only to the melanoma model, since inoculation with the LLC cell line demonstrated significantly decreased tumor growth in Nlrp3-/- animals." (PMID 36032139, 2022). "Similarly, inhibition of NLRP3 by OLT1177 enhances antitumor immunity, thus reducing melanoma growth." (PMID 35530309, 2022). "Absent in melanoma 2, Asc, and caspase-1 p20 increased after ovalbumin exposure while Nlrp3 did not." (PMID 33707120, 2022). "Later, it was demonstrated that NLRP1 rather than NLRP3 promotes melanoma growth and suppresses apoptosis." (PMID 36293159, 2022). "The lack of NLRP3 significantly reduced lung cancer metastasis and improved melanoma survival rate while promoting colorectal cancer metastasis and hepatocellular carcinoma progression." (PMID 35664308, 2022). "We next determined whether NLRP3 inhibition with OLT1177 reduced systemic inflammation, a known tumor-promoting factor in human melanoma." (PMID 33649199, 2021). "The lack of NLRP3 significantly reduced lung metastasis and improved the survival rate of melanoma in response to dendritic cell therapy." (PMID 33776057, 2021). "The analysis revealed that expression of baseline NLRP3/IL-1β levels do not consistently correlate with the IFN-γ signature, which have been positively linked to anti–PD-1 efficacy in melanoma patients." (PMID 33649199, 2021). "To date, various inflammasomes, including NLRP1, NLRP2, NLRP3, absent in melanoma (AIM2) and NLRC4, have been identified." (PMID 31941010, 2020). "This was supported by studies on melanoma that showed constitutive activation of NALP (NLRP3) inflammasomes in melanoma occurred in late‐stage metastatic melanoma but not in intermediate or early‐stage melanoma." (PMID 32027447, 2020). "Among the 14 NLRP protein family members, NLRP3 is the most studied, while NLRP1 is unique because of its caspase recruitment domain (CARD) domain, which allows NLRP1 to directly bind CARD-containing caspases and inhibit melanoma cell apoptosis." (PMID 32899791, 2020). "CRID3, a novel inflammasome inhibitor, exerts its action by inhibiting the NLRP3 and absent in melanoma (AIM) 2 inflammasomes by preventing ASC oligomerization." (PMID 32121312, 2020). "As control served the double-stranded DNA mimic dAdT that signals NLRP3 independently via the DNA sensor absent in melanoma 2 (AIM2), still requiring the adapter molecule ASC as well as caspase-1 for the processing of IL-1β." (PMID 29403480, 2017). "B16F10 mouse melanoma cells, which do not express pro-IL-1β, NLRP3 and AIM2 (data not shown), were chosen to generate B16F10-IL-1β, B16F10-pro-IL-1β (expressing non-secretable IL-1β) and B16F10-vector cells." (PMID 23065753, 2012). "In a mouse model of VCID, CCH activates NOD-like receptor family, pyrin domain containing 3 (NLRP3), absent in melanoma 2 (AIM2) inflammasome in reactive astrocytes in white matter tracts in mouse brain, as shown by higher numbers of AIM2 and NLRP3 in GFAP+ cells at 4 weeks after BCAS procedure." (PMID 38659577, 2024). "Collectively, our findings indicate that melanoma‐derived IL‐1β might represent only a small fraction of the IL‐1β within the tumor microenvironment and targeting NLRP3 would affect primarily immune rather than tumor cells." (PMID 36707938, 2023).
melanoma (continued). "These multiprotein complexes are formed by different members of nucleotide oligomerization domain (NOD)-like receptor family pyrin domain (NLRP1, NLRP2, NLRP3) and absent in melanoma (AIM), but in varicocele pathogenesis, the NLRP3 inflammasome was shown to play an important role." (PMID 36555779, 2022). "Unlike prior studies that have shown NLRP3-dependent release of IL-1β occurs in human melanoma cell lines and tissues derived from more advanced disease, we have been unable to induce IL-1β expression in human melanoma cell lines at significant levels with common NLRP3 stimuli." (PMID 34638239, 2021). "Specifically, related to the activation of the inflammasome, we can see changes in genes such as Nlrp3 (NLR family pyrin domain containing 3), Pycard (often referred to as ASC, apoptosis-associated speck-like protein containing a CARD), or Aim2 (absent in melanoma 2)." (PMID 34413771, 2021). "Interestingly, our results show that IL-1β is not decreased in the TME of melanoma-bearing Nlrp3-/- animals (data not shown), indicating that NLRP3 ablation may promote tumor regression and MDSC subset re-programming via an IL-1β-independent mechanism." (PMID 36032139, 2022). "However, participation of NLRP3 activation in melanoma is not well characterized." (PMID 33649199, 2021). "This process is triggered by the activation of inflammasome molecules, such as NLR family pyrin domain-containing 3 (NLRP3), which is absent in melanoma 2 and involved in the innate immune response to microbial infections and changes in cellular homeostasis." (PMID 41479901, 2025). "The fundamental constituent of inflammasomes, comprising pyrin, the NOD-like receptor (NLR) family (NLRP1, NLRP3, NLRP6, NLRP9, and NLRC4), and absent in melanoma 2 (AIM2)." (PMID 39125817, 2024). "The main contributors to cytokine production in monocytes are the inflammasome, as NLR Family Pyrin Domain Containing 3 (NLRP3) and Absent in Melanoma 2 (AIM2)." (PMID 37915324, 2023). "The main inflammasomes are the IPAF, nod‐like receptor protein 1 (NLRP1), absent in melanoma 2, leucine‐rich repeat and PYD containing 7, and NLRP3 inflammasomes; among them, the NLRP3 inflammasome has been a hot topic in recent years." (PMID 37904713, 2023). "E199L has been reported to be a positive regulator of the NLRP3- (NLR Family Pyrin Domain Containing 3) and AIM2- (Absent in melanoma 2) inflammasome mediated inflammatory response." (PMID 35081156, 2022). "NLRP3 showed no changes in gene expression between control-RPE or AMD-RPE cells, while absent in melanoma 2 (AIM2) was 2.18-fold higher expressed in AMD-RPE cells when compared to control-RPE cells exposed to IL-1α priming and vehicle." (PMID 34202702, 2021). "EIF2AK2 can physically interact with inflammasomes, including NLR family pyrin domain-containing 3 (NLRP3) and Absent in melanoma 2 (AIM2)." (PMID 34759927, 2021). "Pattern recognition receptors involved in inflammasomes comprise nucleotide-binding oligomerization domain and leucine-rich repeat-containing receptors (NLR) such as NLRP3 and NAIP, as well as absent in melanoma-2 (AIM-2)." (PMID 32431703, 2020). "We found that some inflammasome genes, including CARD domain containing 4 (NLRC4), caspase 5 (CASP5), absent in melanoma 2 (AIM2) and the already mentioned NLRP3, were upregulated in our data." (PMID 30935390, 2019). "S. mutans induced IL-1β secretion via caspase-1 activation, and S. mutans-induced IL-1β secretion required absent in melanoma (AIM2), NLR family pyrin domain-containing 3 (NLRP3) and NLR family CARD domain-containing 4 (NLRC4) inflammasome activation." (PMID 30078841, 2018). "Within the NLR family, NLRP1, NLRP3, and NLRC4, as well as the PYHIN family member Absent in Melanoma 2 (AIM2), have been shown to form large multi-protein complexes termed inflammasomes." (PMID 24273542, 2013).
melanoma (continued). "Notably, inhibition of NLRP3 has shown not to increase these cells in PDAC models and to reduce both monocytic MDSCs and PMN-MDSCs in other cancers such as melanoma and lung carcinoma." (PMID 37772994, 2023). "Also, this includes the following four types; the NLRP3/NALP3 inflammasome, the NLRC4/IPAF inflammasome, the NLRP1/NALP1b inflammasome, and the AIM2 (absent in melanoma 2) containing inflammasome." (PMID 34809705, 2021). "Of note, additional studies have indicated that not only NLRP3, but also NLRP1, NLRC4 [NLR (Nod-like receptor) family CARD-containing 4] and AIM2 (absent in melanoma 2) form the inflammasomes that drive inflammation in response to a wide variety of molecular patterns." (PMID 22701621, 2012). "Moreover, a nucleotide-binding oligomerization domain-like receptor (NLR) protein is the main component of inflammasomes and is classified into four types: NLRP1/NALP1b inflammasome, NLRC4/IPAF inflammasome, NLRP3/NALP3 inflammasome, and AIM2 (absent in melanoma 2) containing inflammasome." (PMID 34067673, 2021).
breast cancer (131 papers, 2012 to 2026). A primary or metastatic malignant neoplasm involving the breast. "Within the breast cancer microenvironment, damage-associated molecular patterns (DAMPs) can activate the NLRP3 inflammasome, triggering pyroptosis in CAFs via the NLRP3/caspase-1/GSDMD signaling axis." (PMID 40755775, 2025). "For example, a recent study investigated the ability of cellulose nanofibers and pectin-based 3D hydrogels enriched with 5-fluorouracil to suppress the growth of breast cancer cells and activate NLRP3-associated pyroptosis." (PMID 39940603, 2025). "It has recently been demonstrated that increased expression of the NLRP3 inflammasome in human breast Cancer-Associated Fibroblasts (CAFs) is a precursor to cancer progression and metastasis." (PMID 37715239, 2023). "In breast cancer, NLRP3-expressing macrophages are associated with nodal metastasis, distant metastasis, and poor survival rate." (PMID 36932407, 2023). "First, we observed that MCC950 reversed breast cancer-induced increased expression of NLRP3 inflammasome-associated genes in astrocytes, probably through inhibition of IL-1β and a subsequent feedback effect on priming." (PMID 37749707, 2023). "Anomalous NLRP3 expression was reported in different tumors, and it’s up-regulation in breast cancer-associated fibroblasts (CAFs) is related to cancer progression and metastasis." (PMID 35745570, 2022). "Both native (WT) and NLRP3-deficient THP-1 (THP-1defNLRP3) cells were stimulated with breast cancer-conditioned media (BCM) obtained from MDA-MB-468 cells to study the effect of the tumor secretome on myeloid cells." (PMID 35631400, 2022). "Cancer-associated fibroblast–derived NLRP3 inflammasome and IL-1β facilitated tumor growth and metastasis by modulating the tumor microenvironment towards an immune suppressive milieu in breast cancer." (PMID 35739593, 2022). "In vivo, mice deficient in NLRP3 orthotopically implanted with metastatic breast cancer cell line (E0771) showed significant reduction in tumor growth (p < 0.05) and increased survival (p < 0.01)." (PMID 35631400, 2022). "Intriguingly, cardiac fibroblasts are the main source of NLRP3 inflammasome activity in the heart, whereas the NLRP3 inflammasome in cancer-associated fibroblasts links tissue damage with inflammation in breast cancer progression and metastasis." (PMID 36466820, 2022). "Similar to other studies, our results showed that NLRP3 was decreased in breast cancer tissues and was associated with a favorable prognosis." (PMID 36497253, 2022). "In breast cancer (BC), NLRP3 has been associated with multiple processes including epithelia mesenchymal transition, invasion and metastization." (PMID 35745570, 2022). "It has been demonstrated in the previous studies that the NLRP3 inflammasome and its downstream products are involved in the carcinogenesis of many cancers, including colitis-associated cancer, lung cancer, breast cancer, and melanoma." (PMID 33821998, 2021). "It has recently been demonstrated that up-regulation of NLRP3 inflammasome expression in human breast Cancer-Associated Fibroblasts (CAFs) is a steppingstone to cancer progression and metastasis." (PMID 34540671, 2021). "In silico meta-analysis of the expression of the genes CASP1, NLRP3 and IL-1β in breast cancer exhibited an association with prolonged overall survival." (PMID 33840390, 2021). "Their results indicated an upregulation of the NLRP3 pathway for both murine mammary carcinogenesis and cancer-associated fibroblasts in human breast cancer conditions." (PMID 33015196, 2020). "Taken together, these findings demonstrate a tumour-promoting role for CAF-derived NLRP3/IL-1β, associated with alterations of immune cell infiltration into mammary tumours." (PMID 31558756, 2019).